HDAC8 (histone deacetylase 8)
Diseases named in the same sentence as HDAC8 in open-access papers (continued):
Sharing a sentence is not in itself a finding about the gene and the disease.
leukemia (16 papers, 2014 to 2026). A malignant (clonal) hematologic disorder, involving hematopoietic stem cells and characterized by the presence of primitive or atypical myeloid or lymphoid cells in the bone marrow and the blood. "Using a KMT2A::MLLT3 mouse model, we demonstrate that both genetic knockout and pharmacological inhibition of HDAC8 significantly delayed leukemia progression, prolonged survival and reduced disease recurrence." (PMID 42014858, 2026). "PCI-34051 is a selective HDAC8 inhibitor with 200-fold selectivity compared with other HDACs and has been found to be effective in T-cell lymphoma and leukemia." (PMID 35955780, 2022). "Furthermore, the HDAC8/RAN–XPO5 axis we discovered here can potentially contribute to miR-126 dysregulation in other subsets of leukemia or other cancer types with aberrant HDAC8 activity." (PMID 34686664, 2021). "Recent data also demonstrate that HDAC8 upregulation is an important mechanism to resist FLT3 inhibitors and promote leukemia maintenance; thereafter, HDAC8 inhibition in combination with FLT3 inhibitor treatment could be a promising strategy to treat FLT3-ITD+ AML." (PMID 35656547, 2022). "Furthermore, the previous study has identified that the upregulation of class I HDAC member HDAC8 following FLT3 inhibition contributes to resistance and promotes leukemia maintenance." (PMID 39955584, 2025). "Importantly, treatment with the HDAC8 inhibitor 22d, an ortho-Aryl-N-hydroxycinnamide, selectively induced apoptosis in mouse and human CBFβ-SMMHC expressing leukemia cells." (PMID 27542261, 2016). "Mice expressing the fusion protein but lacking HDAC8 show significantly delayed leukemia development." (PMID 27542261, 2016). "To investigate the significance of Class I HDACs (HDAC1, HDAC2, HDAC3, and HDAC8), HDAC11, and Klfs (Klf1, KLf3, Klf4, and Klf7) in the pathogenesis of human leukemia, we used real-time RT-PCR to evaluate the expression of HDACs and Klfs in bone marrow samples from human leukemia patients." (PMID 25341045, 2014).
lung carcinoma (16 papers, 2015 to 2024). "They linked an indole-based HDAC8-selective inhibitor PCI-34051 with CRBN or VHL ligands and selected CRBN-based compound 16e (SZUH280) with a short PEG linker as the effective HDAC8 degrader in the 549 human lung cancer cell line." (PMID 37667522, 2023). "Another study showed that cAMP can increase HDAC8 expression in lung cancer cells by inhibiting the PI3K/Akt pathway via Epac2/Rap1A activation, which is induced by ISO." (PMID 35910387, 2022). "For example, AMPK‐dependent phosphorylation of HDAC8 promotes lung cancer cell survival under glucose starvation via regulating PGM1 expression." (PMID 34351079, 2021). "However, HDAC8 promotes cisplatin-induced apoptosis in lung cancer cells by repressing Tip41 expression." (PMID 35910387, 2022). "A study found that cAMP increased the expression of histone deacetylase 8 (HDAC8) and increased the apoptosis caused by cisplatin in H1299 lung cancer cells in a way that was neither PKA-dependent nor EPAC-dependent." (PMID 35805104, 2022). "However, one study has shown that Epac2 enhances cisplatin-induced apoptosis in lung cancer cells by promoting the accumulation of HDAC8." (PMID 32899451, 2020). "Another study shows that oxidative stress–mediated repression of HDAC8 induces histone H3 acetylation and HOXA5 expression that controls plasticity of lung cancer stem-like cells." (PMID 33384715, 2020). "Only HDAC8 was significantly repressed by treatment with 1 mM H2O2, suggesting that repression of HDAC8 by oxidative stress is the initial event for acquiring lung cancer stemness." (PMID 27418136, 2016). "In another study, glucose deprivation activated AMP-activated protein kinase-dependent HDAC8 phosphorylation in lung cancer, triggering the elevated expression of PGM1 and promoting the malignant progression of lung cancer, suggesting that PGM1 is a promising anticancer therapeutic target." (PMID 35251177, 2022). "CAMP signaling increases histone deacetylase 8 (HDAC8s) expression through the Epac–Rap1–Akt pathway leading to augmenting cisplatin-induced apoptosis and inhibits radiation-induced ATM phosphorylation promoting apoptosis in lung cancer." (PMID 35419410, 2022).
cardiac hypertrophy (14 papers, 2018 to 2026). "Concerning cardiovascular diseases, HDAC8 is associated with the development of cardiac hypertrophy, fibrosis, inflammation, and hypertension." (PMID 36231123, 2022). "Here we present novel findings demonstrating that, besides HDAC2, HDAC8 is directly implicated in cardiac hypertrophy." (PMID 33959033, 2021). "To determine whether HDAC8 is associated with the regulation of cardiac hypertrophy, we treated isoproterenol-infused mice with the selective HDAC8 inhibitor PCI34051 (30 mg/kg/day) for 5 days." (PMID 33959033, 2021). "Although HDAC2 and HDAC8 promote cardiac hypertrophy, the underlying mechanisms may vary." (PMID 35126818, 2022). "We hypothesized that HDAC8 is associated with the development of cardiac hypertrophy and fibrosis." (PMID 33959033, 2021). "When HDAC8 is re-expressed, miR-21-3p decreases, and the upregulation of p-Gsk3β and p-Akt expression moderately represses cardiac hypertrophy conditions." (PMID 40660005, 2025). "Zhao and colleagues demonstrated that HDAC8 overexpression induces cardiac hypertrophy, which the HDAC8 inhibitor PCI34051 can reduce." (PMID 40660005, 2025). "In summary, HDACs, especially those from class I such as HDAC1, HDAC2, and HDAC8, are key players in the promotion of cardiac hypertrophy through the activation of prohypertrophic signalling pathways and the repression of protective genes." (PMID 40660005, 2025). "HDAC8 inhibition by the inhibitor PCI34051 alleviates cardiac hypertrophy or hypertension induced by isoproterenol and Ang-II." (PMID 40660005, 2025). "Further research by the same group focused on the role of HDAC8 in cardiac hypertrophy and fibrosis in an isoproterenol-induced cardiac hypertrophy mouse model." (PMID 39766311, 2024). "In contrast, it was reported that overexpression of miR-21-3p by AAV markedly reduced cardiac hypertrophy induced by TAC via targeting histone deacetylase-8 and also blocked angiotensin 2 (Ang II-induced cardiac hypertrophy." (PMID 37799562, 2023). "Recently, we reported that Hdac8 inhibition alleviates isoproterenol-induced and angiotensin II-induced cardiac hypertrophy or hypertension in mice." (PMID 35126818, 2022). "Previous studies have demonstrated that HDAC8 regulates cardiac hypertrophy through the AKT/GSK3β pathway." (PMID 35126818, 2022). "This study demonstrated that the HDAC8 selective inhibitor PCI34051 alleviated cardiac hypertrophy, pulmonary congestion, inflammation, and fibrosis, which resulted in improved cardiac functions in the pressure overload-induced heart failure mouse model." (PMID 35126818, 2022). "Recently, the role of HDAC8 was evaluated in cardiac hypertrophy and fibrosis using isoproterenol-induced cardiac hypertrophy model where the expression of HDAC8 is upregulated." (PMID 36077415, 2022). "We investigated the effects of different concentrations of PCI34051 (3, 10, and 30 mg/kg bodyweight/day), an HDAC8 selective inhibitor, on concomitant cardiac hypertrophy using the TAC-induced heart failure mouse model." (PMID 35126818, 2022). "The enzymatic activity of HDAC2 was reported to be critical for the development of cardiac hypertrophy, whereas upregulation of HDAC8 expression was critical for promoting cardiac hypertrophy." (PMID 35126818, 2022). "Recently, we had reported that PCI34051, an HDAC8 selective inhibitor, mitigates angiotensin II-induced hypertension and isoproterenol-induced cardiac hypertrophy." (PMID 35126818, 2022). "The findings of this study suggested that sustained upregulation of Hdac8 mRNA and protein levels has a critical role in the transition from cardiac hypertrophy to heart failure." (PMID 35126818, 2022). "Ectopic expression of HDAC8 induces hypertrophy in cardiomyocytes and upregulates cardiac hypertrophy markers such as ACTA, ANP, BNP, and β-MHC." (PMID 36231123, 2022). "HDAC8 overexpression stimulated cardiac hypertrophy in cells, whereas HDAC8 knockdown reversed those effects." (PMID 33959033, 2021).
cardiac hypertrophy (continued). "To confirm the involvement of HDAC8 in the regulation of cardiac hypertrophy, we used a selective inhibitor and a knockdown technique." (PMID 33959033, 2021). "PCI34051, an HDAC8 selective inhibitor, attenuated cardiac hypertrophy, as determined by HW/BW and HW/TL ratios, cross-sectional areas, and left ventricular posterior and septum thickness in isoproterenol-infused mice." (PMID 33959033, 2021). "The authors also showed that HDAC8 regulates cardiac hypertrophy via the Akt/GSK3β pathway, further supporting our findings." (PMID 33959033, 2021). "We provide evidence that HDAC8 activity and expression partially contribute to the development of cardiac hypertrophy." (PMID 33959033, 2021). "Here we investigated the role of HDAC8 in cardiac hypertrophy and fibrosis using the isoproterenol-induced cardiac hypertrophy model system.Isoproterenol-infused mice were injected with the HDAC8 selective inhibitor PCI34051 (30 mg kg−1 body weight)." (PMID 33959033, 2021). "We showed that the inhibition of HDAC8 enzyme activity or expression attenuated cardiac hypertrophy, whereas HDAC8 overexpression increased cardiac hypertrophy." (PMID 33959033, 2021). "In this study, we investigated the role and regulatory mechanism of HDAC8 in isoproterenol-induced mouse and cellular models of cardiac hypertrophy." (PMID 33959033, 2021). "The treatment with PCI34051, an HDAC8 selective inhibitor, ameliorated cardiac hypertrophy and fibrosis." (PMID 33959033, 2021). "MiR-21-3p protects against cardiac hypertrophy in male mice by regulating histone deacetylase 8 (HDAC8) expression and Akt/Gsk3β signaling, important for growth control in the cardiovascular system." (PMID 32252821, 2020). "Overexpression of miR-21-3p suppressed TAC- and Ang II-induced cardiac hypertrophy by targeting histone deacetylase-8 (HDAC8) and modulating p-AKT/p-GSK3β pathway." (PMID 30013975, 2018). "Taken together, these findings suggest that HDAC8 regulates pro‐cardiac hypertrophy." (PMID 40497340, 2025). "The overexpression of HDAC8 can stimulate cardiac hypertrophy, promote the phosphorylation of p38 MAPK as well as the expression of atrial natriuretic peptide (ANP) and brain natriuretic peptide (BNP) proteins, and inhibit myocardial hypertrophy by blocking HDAC8 activity." (PMID 40710369, 2025). "This study demonstrated that pharmacological inhibition or downregulation of Hdac8 mitigates heart failure-related pathologies, including cardiac hypertrophy, pulmonary congestion, fibrosis, and inflammation in vivo (TAC-induced heart failure mouse model) and in vitro." (PMID 35126818, 2022). "Previous studies have reported that HDAC8 is involved in the induction of cardiac hypertrophy." (PMID 35126818, 2022). "Among Class I HDACs, HDAC2 has been reported to play a key role in cardiac hypertrophy; however, the exact function of HDAC8 remains unknown." (PMID 33959033, 2021). "Next, we investigated the effect of HDAC8 downregulation on cardiac hypertrophy in H9c2 cells." (PMID 33959033, 2021). "To investigate whether HDAC8 regulates p38 MAPK signaling during the isoproterenol-induced cardiac hypertrophy, we performed western blot analysis." (PMID 33959033, 2021). "Targeting HDAC8 could be a novel therapeutic strategy for the treatment of cardiac hypertrophy." (PMID 33959033, 2021). "Among class I HDACs, the roles of HDAC1 and HDAC8 in cardiac hypertrophy remain unknown." (PMID 33959033, 2021). "Furthermore, p38 MAPK inhibitor SB203580 significantly decreased the levels of p38 MAPK phosphorylation, as well as ANP and BNP protein expression, induced by HDAC8 overexpression.Here we show that inhibition of HDAC8 activity or expression suppresses cardiac hypertrophy and fibrosis." (PMID 33959033, 2021). "Previous studies demonstrated that histone deacetylase 8 (HDAC8) inhibition provides protective benefits in several cardiovascular diseases, including heart failure, fibrosis, and cardiac hypertrophy." (PMID 42281825, 2026).
cardiac hypertrophy (continued). "Accordingly, HDAC8 inhibition by PCI-34051 suppresses p38 activation, attenuates markers of cardiac hypertrophy and fibrosis, and suppresses cardiac hypertrophy in vitro and in the isoproterenol-induced cardiac hypertrophy mouse model." (PMID 36231123, 2022). "Isoproterenol induced HDAC8 mRNA and protein expression in mice and H9c2 cells, while PCI34051 treatment decreased cardiac hypertrophy in isoproterenol-treated mice and H9c2 cells." (PMID 33959033, 2021). "HDAC8 serves as a mediator in the promotion of myocardial hypertrophy and fibrosis by modulating gene expression and MAPK and Akt signalling pathways, presenting itself as a potential therapeutic target for addressing myocardial hypertrophy." (PMID 40497340, 2025). "However, the significance of HDAC8 phosphorylation in cardiac hypertrophy is not yet known." (PMID 33959033, 2021).
colorectal cancer (11 papers, 2010 to 2025). A primary or metastatic malignant neoplasm that affects the colon or rectum. "Herein, the current study set out to unravel the association of HDAC8 with colorectal cancer (CRC)." (PMID 36035205, 2022). "We also demonstrated that there was a positive correlation between HDAC8 expression and hypoxia or angiogenesis in other malignant tumors, including ovarian carcinoma, colorectal cancer, prostate cancer, and retinoblastoma, by analyzing the CancerSEA web tool." (PMID 39073752, 2024). "The aim of this study was to investigate the effect of sodium butyrate (NaB) as a histone deacetylase inhibitor (HDACi) on the expression of the HDAC8 gene in the colorectal cancer cell line, and the molecular docking of the LHX1 transcription factor with NaB." (PMID 32788915, 2020). "In this study, the effect of SB on LHX1 as a transcription factor of HDAC8 in colorectal cancer cell lines was investigated." (PMID 31908740, 2019). "The present study demonstrated the potential of novel 3-hydroxyflavone analogues as HDAC8 inhibitors with anticancer property against colorectal cancer." (PMID 30687400, 2018). "Exploiting this feature, the polyphenol quercetin and a series of 3-hydroxyflavone analogues were evaluated for their HDAC8 inhibitory potential and anticancer property against colorectal cancer." (PMID 30687400, 2018). "Class-I HDACs consisting of HDAC1, HDAC2, HDAC3 and HDAC8, are well known oncogenic proteins expressed at high levels in malignant cervical and colorectal cancers." (PMID 29190639, 2017). "To determine the effect of NaB on the mRNA expression of HDAC8 in two human colorectal cancer cell lines (HT-29 and HCT-116), we treated cell lines with different concentrations of NaB based on IC50 for 24 and 48 hours and subsequently, mRNA expression was determined by Real-Time PCR." (PMID 32788915, 2020). "Therefore, in this study, we evaluated the effects of NaB on mRNA expression of the HDAC8 gene in human colorectal cancer cell lines and also how the drug affects gene expression." (PMID 32788915, 2020). "Thus, the present study identified the potentials of novel 3-hydroxyflavone analogues as HDAC8 inhibitors with anticancer property against colorectal cancer providing a lead for new drug development." (PMID 30687400, 2018). "Thus, in the present study, the polyphenol quercetin and a series of synthetic 3-hydroxyflavone analogues were evaluated for their in vitro HDAC8 inhibition and anticancer potential along with in vivo antitumor effects against colorectal cancer." (PMID 30687400, 2018). "We also demonstrated that MPT0G236 inhibited the activity of Class I HDACs (HDAC1, HDAC2, HDAC3, and HDAC8), as well as of a Class IIb HDAC, HDAC6, leading to the increased acetylation of α-tubulin and histone H3 in both colorectal cancer cells." (PMID 37628767, 2023). "In the present study, we also investigated the effects of NaB on HDAC8 mRNA expression in two HCT-116 and HT-29 human colorectal cancer cell lines." (PMID 32788915, 2020). "In this study, we used the human colorectal carcinoma HCT-116 and the colorectal adenocarcinoma HT-29 cell lines, in order to investigate the effects of NaB on HDAC8 gene expression." (PMID 32788915, 2020). "Finally, the results of this study showed that NaB could downregulate HDAC8 expression to inhibit the growth of HT-29 and HCT-116 human colorectal cancer cell lines and promote cell apoptosis." (PMID 32788915, 2020).
glioma (11 papers, 2015 to 2024). A benign or malignant brain and spinal cord tumor that arises from glial cells (astrocytes, oligodendrocytes, ependymal cells). "In a recent study, the histone deacetylase HDAC8 was implicated in the modulation of the glioma immune response." (PMID 37217462, 2023). "HDAC8 regulates human and mouse glioma cell viability and tumor migration through a-tubulin acetylation." (PMID 37217462, 2023). "It was further shown that expression of histone deacetylase 8 (HDAC8) was responsible for the activation of the Wnt/β-catenin/c-Myc/cyclin D1/Sox2 signaling and glioma cell resistance to TMZ." (PMID 35626024, 2022). "Recently, Histone Deacetylase 8 (HDAC8) was shown to modulate glioma immune responses through regulation of NKG2D ligands." (PMID 35565467, 2022). "HDAC8 promotes glioma migration by regulating the acetylation levels of α-tubulin, which is important in microtubule structural organization and cell migration." (PMID 36231123, 2022). "Specifically, the mRNA level of HDAC1 (p = 1.25e−13), HDAC3 (p = 2.51e−09), HDAC7 (p = 1.43e−19), and HDAC8 (p = 3.48e−10) showed an increasing trend with glioma grade progressing." (PMID 34540896, 2021). "The authors found that inhibiting HDAC8 with a specific inhibitor, PCI-34051, reduced tumor volume in glioma mouse models." (PMID 37217462, 2023). "HDAC8 inhibition by PCI-34051 treatment elevates acetylated α-tubulin and reduces cell migration in glioma cells." (PMID 36231123, 2022). "However, HDAC8 mRNA expression levels were not meaningful for prognostic survival analyses of patients with glioma." (PMID 35359455, 2022). "HDAC8 and HDAC9 expression levelswere not significantly changed in gliomas as compared to control patients." (PMID 25791281, 2015).